PKHD1 (PKHD1 ciliary IPT domain containing fibrocystin/polyductin)
Description:
Promotes ciliogenesis in renal epithelial cells and therefore participates in the tubules formation and/ or ensures the maintenance of the architecture of the lumen of the kidney (By similarity). Has an impact on cellular symmetry by ensuring correct bipolar cell division through the regulation of centrosome duplication and mitotic spindle assembly and by maintaining oriented cell division (OCD) during tubular elongation through planar cell polarity (PCP) pathway. During epithelial cell morphogenesis, it also regulates cell-cell and cell-matrix adhesion and participates in cell motility (By similarity). Promotes cell-cell contact through the positive regulation of PTK2 kinase activity leading to either positive regulation of epithelial cell proliferation through the HRAS/RAF1 pathways, or negative regulation of apoptosis through the PDK1/AKT1 pathway (By similarity). May act in collecting-duct and biliary differentiation. May participate in the regulation of the cholangiocytes proliferation and the CCN2 production in an CXCL8-dependent manner.
Synonyms: FCYT; TIGM1; ARPKD; FPC; PCYT; PKD4
Tractability: Antibody: UniProt places it where antibodies can reach, with high confidence; UniProt predicts a signal peptide or a membrane-spanning region; its Gene Ontology location is reachable by antibodies, with medium confidence.
Gene: Protein-coding gene on chromosome 6 (51,615,299 to 52,087,613, reverse strand). Ensembl gene ENSG00000170927.
Subcellular location: Cell membrane; Cytoplasm; Cell projection, cilium; Cytoplasm, cytoskeleton, cilium basal body; Cytoplasm, cytoskeleton, spindle; Chromosome, centromere; Apical cell membrane; Nucleus; Secreted, extracellular exosome; Secreted; Endoplasmic reticulum; Golgi apparatus
Subcellular location (Human Protein Atlas): Cytosol; Primary cilium; Basal body
Gene Ontology:
Molecular function: protein binding; signaling receptor activity
Biological process: intracellular calcium ion homeostasis; negative regulation of apoptotic process; positive regulation of cell population proliferation; regulation of centrosome duplication; regulation of cholangiocyte proliferation; regulation of ERK1 and ERK2 cascade; regulation of TOR signaling; branching morphogenesis of an epithelial tube; cell-cell adhesion; cell-cell junction organization; epithelial cell morphogenesis; establishment of centrosome localization; establishment of mitotic spindle orientation; homeostatic process; negative regulation of epithelial cell apoptotic process; positive regulation of epithelial cell proliferation; regulation of cell adhesion; regulation of cell-cell adhesion; regulation of cell-matrix adhesion; regulation of establishment of planar polarity
Cellular component: apical plasma membrane; centrosome; ciliary basal body; cilium; cytoplasm; cytosol; extracellular exosome; mitotic spindle; perinuclear region of cytoplasm; plasma membrane; endoplasmic reticulum; external side of plasma membrane; extracellular region; Golgi apparatus; nucleus; 9+0 non-motile cilium; chromosome, centromeric region; spindle
Genetic constraint (gnomAD): Loss-of-function variants: 212 observed, 303.22 expected, observed/expected ratio (o/e) 0.7, 90% interval 0.62 to 0.78. The upper end of that interval is the gene's LOEUF score, 0.78, which puts it in group 3 of 6, group 1 being the genes least tolerant of losing a copy. Missense variants: 3,894 observed, 4,208 expected, observed/expected ratio (o/e) 0.93, 90% interval 0.9 to 0.95. Synonymous variants: 1,447 observed, 1,581.3 expected, observed/expected ratio (o/e) 0.92, 90% interval 0.88 to 0.96.
Gene-disease validity (ClinGen):
ClinGen rates the evidence that PKHD1 causes each of these diseases.
autosomal recessive polycystic kidney disease (autosomal recessive): Definitive. An inherited disorder characterized by the development of cysts affecting the collecting ducts.
Homologues: Orthologues: chimpanzee PKHD1 (99% identical), macaque PKHD1 (95% identical), dog PKHD1 (80% identical), rabbit PKHD1 (78% identical), pig PKHD1 (76% identical), guinea pig PKHD1 (75% identical), mouse Pkhd1 (72% identical), rat Pkhd1 (72% identical), tropical clawed frog pkhd1 (42% identical). Paralogues in human: PKHD1L1 (25% identical), DST (9% identical), MACF1 (8% identical), PLEC (8% identical), SYNE1 (8% identical), SYNE2 (7% identical), SPTBN2 (7% identical), FLNC (7% identical), FLNA (6% identical), SPTBN1 (6% identical), SPTBN4 (6% identical), SPTBN5 (6% identical), and 24 more.
Diseases named in the same sentence as PKHD1 in open-access papers:
PKHD1 is named in the same sentence as 100 diseases in open-access papers, as found by Europe PMC text mining. Sharing a sentence is not in itself a finding about the gene and the disease. The quoted sentences say what the papers report.
autosomal recessive polycystic kidney disease (85 papers, 2007 to 2026). "Autosomal recessive polycystic kidney disease (ARPKD) is a pediatric genetic nephropathy caused by mutations in PKHD1, which encodes fibrocystin." (PMID 42305588, 2026). "Background/Objectives: Autosomal recessive polycystic kidney disease (ARPKD) is a severe ciliopathy caused by biallelic pathogenic variants in PKHD1, characterized by variable renal and hepatobiliary involvement." (PMID 41751613, 2026). "PKHD1, the gene primarily mutated in human autosomal recessive polycystic kidney disease, is one of the top 20 genes associated with primary open angle glaucoma (POAG) and associated endophenotypes in Genome-Wide Association Studies." (PMID 41757104, 2026). "In this subgroup, PKHD1-associated autosomal recessive polycystic kidney disease had the most substantial contribution of a single diagnosis to the overall lifetime risk." (PMID 40677321, 2025). "Variants in PKHD1, primarily associated with autosomal recessive polycystic kidney disease (ARPKD), can also lead to a broad range of phenotypes, from asymptomatic cases to severe liver and/or kidney involvement with perinatal lethality." (PMID 41044823, 2025). "The 3 disorders with the highest lifetime risk (>1.5 per 100,000), accounted for 24% of the overall lifetime risk and were caused by PKHD1 (autosomal recessive polycystic kidney disease), SLC12A3 (Gitelman syndrome), and COL4A3 (Alport syndrome) variants." (PMID 40677321, 2025). "Multiple reports have demonstrated that PKHD1 mutations are responsible for autosomal recessive polycystic kidney disease (ARPKD) and Caroli syndrome (CD)." (PMID 38388441, 2024). "The authors stated that PKHD1 is currently the only known disease‐causing gene for autosomal recessive polycystic kidney disease (ARPKD)." (PMID 40626244, 2024). "It has been confirmed that PKHD1 mutation is the primary cause of autosomal recessive polycystic kidney disease (ARPKD)." (PMID 38388441, 2024). "On the other hand, mutations in the PKHD1 gene can lead to the development of the recessive form of autosomal recessive polycystic kidney disease (ARPKD), typically starting in infancy." (PMID 39200287, 2024). "The aim of this study was to determine the effects of MET on cyst growth, kidney function, AMPK and mTOR signaling, and lactate levels in male PCK rats, a Pkhd1 gene mutation model of human autosomal recessive polycystic kidney disease (ARPKD)." (PMID 37653564, 2023). "PKHD1 gene mutations were identified in Caroli disease associated with autosomal recessive polycystic kidney disease (ARPKD)." (PMID 35741793, 2022). "Autosomal recessive polycystic kidney disease (ARPKD) is associated with variants in the PKHD1 gene with manifestation typically in infancy or in childhood." (PMID 36406818, 2022). "In the Afrikaner population, a founder mutation, apM627 K substitution at the PKHD1 locus is associated with Autosomal Recessive Polycystic Kidney Disease (ARPKD)." (PMID 36672600, 2022). "The disease is in most cases caused by variants in the gene Polycystic Kidney and Hepatic Disease 1 (PKHD1) on chromosome 6." (PMID 33594464, 2021). "Both CD and ARPKD are rare autosomal recessive disorders, and both are claimed to be related to mutations in polycystic kidney and hepatic disease 1 (PKHD1) (i.e., the only pathogenic gene currently known)." (PMID 33845788, 2021). "Physicians believe that Caroli disease (which refers to type V biliary cysts) is a special type of biliary cyst caused by a mutation in the PKHD1 gene and is associated with autosomal recessive polycystic kidney disease (ARPKD)." (PMID 32957915, 2020). "It is caused by mutations of the PKHD1 gene (polycystic kidney and hepatic disease-1, also known as ciliary IPT domain containing fibrocystin/polyductin) on chromosome 6p12." (PMID 33059727, 2020). "In some cases, this syndrome has been associated with PKHD1 mutations, which are also known to cause autosomal recessive polycystic kidney disease." (PMID 31741824, 2019).
autosomal recessive polycystic kidney disease (continued). "This missense mutation has been recorded in the public ARPKD (autosomal recessive polycystic kidney disease)/PKHD1 database." (PMID 28814334, 2017). "Autosomal recessive polycystic kidney disease is caused by mutations in a single gene, polycystic kidney and hepatic disease 1 (PKHD1), encoding the ciliary protein fibrocystin/polyductin." (PMID 28296980, 2017). "The disease is caused by mutations in a single gene, Polycystic Kidney and Hepatic Disease 1 (PKHD1) encoding a huge transmembrane protein of poorly understood function called fibrocystin (4074 amino acids)." (PMID 25886171, 2015). "Mutations affecting the ciliary localized receptor fibrocystin (PKHD1) cause autosomal recessive polycystic kidney disease, which affects approximately 1∶20,000 individuals." (PMID 24586199, 2014). "Mutations in the fibrocystin gene (PKHD1) are responsible for autosomal recessive polycystic kidney disease, a disorder afflicting approximately 1 in 20,000 individuals and a cause of significant mortality during the first year of life." (PMID 24586199, 2014). "Amniocentesis was performed for karyotype and to search for mutations in the PKHD1 for the presumptive diagnosis of autosomal recessive polycystic kidney disease (ARPKD)." (PMID 25114813, 2014). "The Ptprn2 locus is reported to be hypermethylated in lung cancer while Pkhd1 (polycystic kidney and hepatic disease 1) is associated with polycystic kidney and hepatic disease." (PMID 19812696, 2009). "Renal biopsy confirmed immune complex-mediated MPGN (IC-MPGN), and genetic testing revealed a homozygous, pathogenic missense PKHD1 variant (NM_138694.3:c.4870C > T; p.(Arg1624Trp), leading to a diagnosis of autosomal recessive polycystic kidney disease (ARPKD)." (PMID 41884136, 2026). "We also detected one case each (2.5% of total abnormalities) of Wilson’s disease (mutations in ATP7B), cystic fibrosis (mutations in CFTR), Cockayne syndrome (mutations in ERCC6), auditory neuropathy (mutations in OTOF), and autosomal recessive polycystic kidney disease (mutations in PKHD1)." (PMID 41329681, 2025). "The study also identified pathogenic mutations in PKD1 and PKHD1, responsible for autosomal dominant and autosomal recessive polycystic kidney disease, respectively, demonstrating the utility of NGS in resolving genetically complex regions and improving diagnostic yield." (PMID 41288877, 2025). "We made a major breakthrough in understanding how this region causes disease, using RNA-seq to show that Pkhd1 (Polycystic Kidney and Hepatic Disease 1), which is upstream on chromosome 1, is mutated in NOD.Abd3 mice with truncation after exon 35 (designated “Pkhd1del36−67”)." (PMID 36097289, 2023). "The gene that causes the ARPKD is polycystic kidney and hepatic disease 1 (PKHD1)." (PMID 37830491, 2023). "The seven probands with inherited renal structural abnormality included four autosomal recessive polycystic kidney disease (ARPKD) caused by the compound heterozygous variants in PKHD1 and three autosomal dominant polycystic kidney disease (ADPKD) caused by the heterozygous variants in PKD1." (PMID 36685964, 2022). "Autosomal recessive polycystic kidney disease (ARPKD) is caused by mutations in the PKHD1 gene." (PMID 34536170, 2022). "Mutations of the Pkhd1 gene cause autosomal recessive polycystic kidney disease (ARPKD)." (PMID 32698519, 2020). "PKHD1 is known to cause autosomal recessive Polycystic Kidney Disease (MIM #606702)." (PMID 30809968, 2019). "In addition to PKHD1 (polycystic kidney and hepatic disease 1), mutations in DZIP1L (DAZ interacting zinc finger protein 1 like) have recently been associated with ARPKD." (PMID 30003073, 2018). "In addition, PKHD1 (polycystic kidney and hepatic disease 1) gene mutational analysis revealed a paternally inherited heterozygous missense mutation (c.1877A > G, p.Lys626Arg)." (PMID 28814334, 2017).
autosomal recessive polycystic kidney disease (continued). "Indeed, Autosomal Recessive Polycystic Kidney Disease (ARPKD) is caused by mutations in PKHD1, which codes for fibrocystin/polyductin, a protein associated with the apical membrane and the primary cilium." (PMID 26125584, 2015). "Biallelic PKHD1 mutations cause autosomal recessive polycystic kidney disease (ARPKD) while monoallelic variants cause ADPKD with a milder presentation." (PMID 40268755, 2025). "Autosomal recessive polycystic kidney disease (ARPKD) is a rare ciliopathy caused by homozygous or compound heterozygous mutations in the polycystic kidney and hepatic disease 1 gene (PKHD1)." (PMID 36835961, 2023). "Autosomal recessive polycystic kidney disease (ARPKD) is an inherited pathology caused mainly by mutations of the polycystic kidney and hepatic disease 1 (PKHD1) gene, which usually leads to end‐stage renal disease." (PMID 36353932, 2022). "Autosomal recessive polycystic kidney disease (ARPKD) due to PKHD1 mutation is characterized by severe hepatic fibrosis with bile duct dysplasia and intrahepatic periportal fibrosis." (PMID 34980882, 2022). "Variants in fibrocystin (encoded by the PKHD1 gene) worsen the ramifications of the autosomal recessive polycystic kidney disease (ARPKD) in children and adults." (PMID 35328087, 2022). "Autosomal recessive polycystic kidney disease (ARPKD) is mainly a result of the biallelic pathogenic variants in the PKHD1 (PKD type 4) and DZIP1L (PKD type 5) genes, besides numerous syndromic PKD genes." (PMID 34032358, 2021). "Caroli disease is an autosomal recessive genetic disease that is caused by a mutation in the PKHD1 gene located on chromosome 6p12; usually, it is considered to be associated with autosomal recessive polycystic kidney disease (ARPKD)." (PMID 32957915, 2020). "One patient with an ascertained mutation in the gene PKHD1 was suffering from an autosomal recessive polycystic kidney disease (ARPKD) and additionally from a double kidney with an ectopic entering ureter and a contralateral VUR." (PMID 32612963, 2020). "PKHD1 is the main genetic cause of autosomal recessive polycystic kidney disease (ARPKD), a hereditary hepato-renal fibrocystic disorder which is the most important cause of end-stage renal disease during early childhood." (PMID 33059616, 2020). "Autosomal recessive polycystic kidney disease (ARPKD) is a severe and early‐onset hepatorenal fibrocystic disease, mainly caused by variants in the PKHD1 gene." (PMID 33112055, 2020). "Autosomal recessive polycystic kidney disease (ARPKD) is a severe and mostly early-onset hepatorenal disorder mainly caused by mutations in the PKHD1 gene." (PMID 32994492, 2020). "Autosomal recessive polycystic kidney disease (ARPKD) is one of the ciliopathies and is caused by mutations of the PKHD1 gene, encoding fibrocystin." (PMID 29322327, 2018). "Autosomal recessive polycystic kidney disease (ARPKD) is a severe monogenic disorder that occurs due to mutations in the PKHD1 gene." (PMID 27891514, 2016). "Autosomal recessive polycystic kidney disease (ARPKD) is caused by mutations in the PKHD1-gene on chromosome 6." (PMID 18810502, 2010). "The highest lifetime risk (> 1.5 per 100,000) was estimated for nephropathies caused by variants in PKHD1, SLC12A3, and COL4A3 associated with autosomal recessive polycystic kidney disease, Gitelman syndrome, and Alport syndrome, respectively." (PMID 40677321, 2025). "CS is frequently associated with autosomal recessive polycystic kidney disease (ARPKD), which is caused by pathogenic mutations in the polycystic kidney and hepatic disease 1 (PKHD1) gene." (PMID 41039418, 2025). "It is part of the clinical spectrum of autosomal recessive polycystic kidney disease (ARPKD), resulting from mutations in the PKHD1 gene." (PMID 39429706, 2025). "Autosomal recessive polycystic kidney disease (ARPKD) is caused by mutations in the PKHD1 gene, which encodes the fibrocystin/polyductin (FPC) protein." (PMID 40136708, 2025).